TDP2 (tyrosyl-DNA phosphodiesterase 2)
Diseases named in the same sentence as TDP2 in open-access papers (continued):
Sharing a sentence is not in itself a finding about the gene and the disease.
prostatic hyperplasia (1 paper, 2020). "The loss of TDP2 caused the abnormal proliferation of epithelial cells following three times daily injection of androgens into 2‐month‐old mice and also resulted in progressive prostate hyperplasia in 2‐ and 6‐month‐old mice." (PMID 32277721, 2020). "Another unresolved question is the role played by TDP2 in the prevention of prostatic hyperplasia and oncogenesis." (PMID 32277721, 2020).
Telangiectasia (1 paper, 2020). Telangiectasias refer to small dilated blood vessels located near the surface of the skin or mucous membranes, measuring between 0.5 and 1 millimeter in diameter. "The tyrosyl-DNA phosphodiesterase 2 (TDP2), and more recently reported DNA topoisomerases as well as ataxia telangiectasia mutated pathway and Rad3-related pathway and signaling factor CHK1 (ATR-CHK1), which were shown to take part in the synthesis of HBV cccDNA, may serve as examples." (PMID 33171788, 2020).
thymic lymphoma (1 paper, 2020). "Single Tdp2−/− mice had a lifespan comparable to wild-type, and none of the animals developed thymic lymphoma within the course of the experiment (2 years)." (PMID 32060399, 2020).
thymic tumour (1 paper, 2020). "In summary, we can conclude that loss of TDP2 increases the incidence of the same oncogenic rearrangements that drive thymic tumour in Atm−/− animals, suggesting a strong contribution of TOP2-mediated lesions to ATM-deficient T-cell cancer predisposition." (PMID 32060399, 2020). "Strikingly however, in Atm−/− background, both the reduced overall life-span and the incidence of thymic tumours were largely aggravated by Tdp2 inactivation." (PMID 32060399, 2020). "Here, we unexpectedly find that specifically disturbing the repair of DSBs produced by DNA topoisomerase II (TOP2) by genetically removing the highly specialised repair enzyme TDP2 increases the incidence of thymic tumours in Atm−/− mice." (PMID 32060399, 2020). "Interestingly, thymic tumours in Tdp2−/−Atm−/− mice display identical characteristics to those of Atm−/− animals, with a very aggressive form of T-ALL associated to recurrent clonal genome rearrangements enriched at loci undergoing V(D)J recombination." (PMID 32060399, 2020). "Thus, Tdp2−/−Atm−/− mice showed a median survival of 140 days, contrasting with 307 days for the Atm−/− single mutant, and the probability of developing a thymic tumour during the 1st year of life increased from a 43% in Atm−/− to a 72% in the Tdp2−/−Atm−/− double mutant." (PMID 32060399, 2020). "In order to gain insights into the molecular events responsible for thymic tumour development in Tdp2−/−Atm−/− mice, we analysed and compared copy-number variation by comparative genomic hybridization (CGH) in six Tdp2−/−Atm−/− and three Atm−/− thymic tumours." (PMID 32060399, 2020). "Importantly, lifespan of Tdp2−/−Atm−/− and Atm−/− mice that did develop a thymic tumour was not significantly different, suggesting a direct effect on the incidence and not on the latency or aggressiveness of T-cell malignancies." (PMID 32060399, 2020).
cancer (24 papers, 2013 to 2026). A tumor composed of atypical neoplastic, often pleomorphic cells that invade other tissues. "Understanding the role of TDP2 in DPC repair in animal models is of great importance for the treatment of cancer and potentially for the treatment of neurological disorders associated with loss of TDP2 function." (PMID 39228401, 2024). "It is notable that TOP2 poisons are used widely in the clinic to treat a variety of cancers, and we point out that the use of these agents in patients with TDP2 mutations should be avoided or at the very least treated with extreme caution." (PMID 30109272, 2018). "The potential causal relationship between the loss of TDP2 and the oncogenesis is suggested by TCGA database, which shows that homozygous deep deletion of the TDP2 gene is seen in 0.4% and 0.8% of the cancers arising in the breast and prostate tissues, respectively, but not in other cancer types." (PMID 32277721, 2020). "TDP2 (Tyrosyl-DNA phosphodiesterase 2), a DNA repair enzyme, has recently attracted increasing attention for its potential role in cancer biology." (PMID 41481587, 2026). "Elucidation of the TDP2-dependent repair pathway for DSBs induced by radiomimetic drugs revealed that the combination of radiomimetic drugs, TDP1 inhibitors, and TDP2 inhibitors can be used for cancer treatment." (PMID 40155951, 2025). "Given the widespread use of TOP1 and TOP2 inhibitors in cancer therapy, the data obtained in the present study raise the possibility that TDP2 is a critical etiological factor in the response of tumors to TOP1 and TOP2 inhibitors." (PMID 37392847, 2023). "It is also conceivable that the use of such TDP2 inhibitors will have immense clinical benefits for cancer treatment." (PMID 37392847, 2023). "ZW-1266 is a cell-permeable deazaflavin analog that selectively inhibits TDP2 activity and sensitizes cancer cells toward ETP-treatment." (PMID 32193368, 2020). "Since TDP1 and TDP2 are rational anti-cancer drug targets, it will be beneficial to verify how potential inhibitors will impact TDP1 and TDP2 in the nucleus vs the mitochondria." (PMID 31226795, 2019). "As expected, in comparison with non-targeting shRNA/siRNA control (shGIPZ + siCtrl), knockdown of TDP2 in both A549 (shGIPZ + siTDP2) and H460 (shGIPZ + siTDP2) sensitized cancer cells to etoposide-induced cell growth inhibition." (PMID 26701725, 2016). "TDP2 regulates cancer cells’ response to DNA damage and growth inhibition induced by Top2 inhibitors." (PMID 26701725, 2016). "Tyrosyl DNA phosphodiesterase 2 (TDP2) repairs Topoisomerase 2 (Top2)-linked DNA damage, thereby protecting cancer cells against Top2 inhibitors-induced growth inhibition and cell death." (PMID 26701725, 2016). "Much interest has been seen recently on investigating TDP2 as it repairs Top2-mediated DNA damage and confers cancer cells’ resistance to Top2 inhibitors." (PMID 26701725, 2016). "TDP2 facilitates therapeutic resistance to topoisomerase poisons, which are widely used in the treatment of a range of cancer types." (PMID 27099339, 2016). "Considering that the mechanisms of drug action for UCH37 and TDP2 differ significantly, the potential for drugs targeting both of them is likely to be more efficient than targeting independent mechanisms in the cancer cell." (PMID 25991664, 2015). "Given the widespread use of TOP2 poisons in cancer chemotherapy, this raises the possibility of TDP2 being an important etiological factor in the response of tumours to this type of agent and in the development of treatment-related malignancy." (PMID 23505375, 2013). "To determine the impact of TDP2 on TOP2-induced DNA damage in mammals, and thus its possible relevance to anti-cancer therapy, we adopted a mouse model in which the first three exons of Tdp2, plus the 5′-UTR, were deleted by Cre-mediated excision." (PMID 23505375, 2013).
cancer (continued). "Here, we employ avian and murine experimental models to show that TDP2/Tdp2 deletion results in hypersensitivity to a structurally diverse range of anti-cancer TOP2 poisons." (PMID 23505375, 2013). "In this study, we identified TDP2 as a susceptible gene in the absence of TDP1 to target cancers with radiomimetic drugs." (PMID 40155951, 2025). "Our findings also extend the understanding of TDP2’s role in cancer progression." (PMID 40728977, 2025). "Interestingly, most of these genes are linked with cancer processes (Pld1, Fam13c, Svbp, TMem192, Zc3h7a, RTP4, Naa30, Zgrf1, Slc33a1, Dnmt3b, Map6, Plin4, Eps8L2, Alg12, Capg and Tdp2)." (PMID 37700325, 2023). "Our findings support this hypothesis, as TDP2 KD cancer cells exhibited reduced cell proliferation, disturbed cell cycle profiles, and increased sensitivity to ACP52C compared to mock cells." (PMID 37845006, 2023). "On the other hand, the dynamic range of expression of different TDP2 isoforms across different human cancer cell lines could, in fact, be a reflection of distinct regulatory mechanisms in different cell lines." (PMID 31226795, 2019). "Thus inhibiting TDP2 activity would sensitize cancer cells’ to Top2 inhibitors-induced growth inhibition and killing, thereby increasing the therapeutic efficacy and decreasing the toxicity of Top2 inhibitors in cancer treatment." (PMID 26701725, 2016). "However, this increase was ∼2-fold higher in Tdp2Δ1–3 mice than in wild type mice, suggesting that TDP2 protects heamatopoietic cells from genome instability induced by anti-cancer TOP2 poisons." (PMID 23505375, 2013). "Additionally, TDP2’s interactions within DNA repair pathways and oncogenic signaling further establish its role in cancer progression and therapeutic responses, making it a promising target for personalized cancer treatment approaches." (PMID 40728977, 2025). "Our aim was to investigate the role of Tdp2 in DPC repair using zebrafish, a powerful model organism to study DNA repair and its effects on aging, cancer, and neurodegeneration." (PMID 39228401, 2024). "Topoisomerase 1 (TOP1) and tyrosyl DNA phosphodiesterase 2 (TDP2) were among the nucleic acid transcripts of choice due to their role as genomic instability biomarkers and their implication in various cancers and neurologic disorders." (PMID 30555231, 2018). "As such, our study revealed a post-translational regulation of TDP2 activity and discovered a new role of ERK3 in increasing cancer cells’ DNA damage response and chemoresistance to Top2 inhibitors." (PMID 26701725, 2016). "Knockdown of either ERK3 (siCtrl/shERK3), TDP2 (siTDP2/shGIPZ) or both (siTDP2/shERK3) greatly increased the levels of cleaved PARP-1, suggesting that ERK3 and TDP2 also protects cancer cells against etoposide-induced apoptosis." (PMID 26701725, 2016). "In this study, we identified TDP2 as a new target of ERK3 and they work together to protect cancer cells against Top2 inhibitors-induced DNA damage and growth inhibition." (PMID 26701725, 2016). "The discovery of this novel TDP2-dependent repair of DSBs resulting from radiomimetic drug exposure indicates that TDP1 and TDP2 inhibition in combination with radiomimetic drugs represents a strategy for cancer treatment." (PMID 40155951, 2025). "Therefore, TDP2 inhibition combined with a TOP1 inhibitor and radiomimetic drugs results in cancer cell sensitization." (PMID 40155951, 2025). "Therefore, multi-target drugs affecting several cancer mechanisms represented by UCH37 and TDP2 could be more efficient." (PMID 25991664, 2015).
cancer (continued). "Notably, consistent with its enzyme activity, TDP2 is required for cellular resistance to the anti-cancer TOP2 poison etoposide, but is not required for cellular resistance to ionizing radiation or methylmethane sulphonate; agents that induce DNA damage independently of TOP2 activity." (PMID 23505375, 2013). "ZW-1266 is a cell-permeable deazaflavin analog that selectively inhibits TDP2, but not TDP1 enzymatic activity in vitro, and strongly sensitizes cancer cells toward the treatment of ETP, a phenotype consistent with the TDP2 function loss and leads to the Top2cc formation." (PMID 32193368, 2020). "Given the widespread use of TOP2 poisons in cancer therapy, and the observed hypersensitivity to TOP2 poisons of cells lacking TDP2, our findings suggest that TDP2 could affect the response of tumour cells to chemotherapy." (PMID 23505375, 2013).
tumor (12 papers, 2013 to 2026). "By integrating bulk RNA sequencing data from TCGA and scRNA-seq analysis, we investigated the association between TDP2 expression and immune-related pathways, as well as its role in mediating tumor-immune interactions." (PMID 41481587, 2026). "Here, the authors develop a Tdp2−/−Atm−/− double-deficient mouse model to uncover topoisomerase II-induced DSBs as significant drivers of the genomic rearrangements that underpin these tumours." (PMID 32060399, 2020). "In this study, TDP2 high expression was associated with upregulated GALECTIN signaling, further supporting its role in immune suppression and tumor progression." (PMID 41481587, 2026). "In this study, we explored the role of TDP2 in modulating the tumor microenvironment (TME) through single-cell RNA sequencing and pathway enrichment analysis." (PMID 41481587, 2026). "By interacting with fibroblasts, myeloid cells, and macrophages, TDP2 high expression enhances immune evasion and promotes tumor invasiveness through the COLLAGEN, GALECTIN, MK, and OSM signaling pathways." (PMID 41481587, 2026). "The results showed that TDP2 KD significantly inhibited tumor growth in mice, especially in immunocompetent C57BL/6J mice." (PMID 41481587, 2026). "Our study revealed that TDP2 high cells interact with fibroblasts to increase the synthesis and degradation of collagen, thereby promoting tumor cell invasion." (PMID 41481587, 2026). "This pathway, involved in RNA metabolism and cell cycle progression, highlights TDP2’s role in enhancing tumor aggressiveness." (PMID 41481587, 2026). "Our findings highlight TDP2 as a crucial regulator of immune suppression in PRAD and provide a rationale for targeting TDP2 to enhance anti-tumor immunity and improve patient outcomes." (PMID 41481587, 2026). "Previous results have demonstrated the effects of TDP2-overexpressing epithelial cells 2 on the tumor microenvironment." (PMID 41481587, 2026). "Our results revealed that epithelial cells with high TDP2 expression extensively interact with myeloid cells, macrophages, and fibroblasts, thereby shaping immune responses and facilitating tumor progression." (PMID 41481587, 2026). "The MK signaling pathway was also enriched in TDP2 high-expressing cells, promoting tumor cell proliferation and migration, particularly through interactions with myeloid cells and fibroblasts." (PMID 41481587, 2026). "Focusing on the broad substrate spectrum of TDP2, the inhibition of TDP2 is an attractive target for tumor cell sensitization in combination with TOP1 inhibitors and CTNAs." (PMID 37392847, 2023). "TDP2, however, is shown to be lowly expressed in the in-house tumor samples, TCGA CRC tumor samples, and pre-surgical cfRNA." (PMID 37091184, 2023). "This suggests that Tdp2−/−Atm−/− tumours likely reflect direct functions of ATM in the repair of TOP2-induced DSBs, and not only in their signalling for checkpoint and apoptosis." (PMID 32060399, 2020). "In this sense, tumours observed in Tdp2−/−Atm−/−mice were also predominantly formed by double positive CD4+ CD8+ T-cell precursors (80%)." (PMID 32060399, 2020). "Activation of the MK signaling pathway promotes tumor cell proliferation and migration, particularly in the interaction between TDP2 high-expressing epithelial cells and myeloid cells and fibroblasts, driving remodeling of the tumor microenvironment and invasiveness." (PMID 41481587, 2026). "Notably, tumor cells with elevated TDP2 expression exhibit increased interactions with components of the TME, potentially suppressing anti-tumor immunity and facilitating tumor progression." (PMID 41481587, 2026). "TDP2 might therefore be a valid target for overcoming tumour resistance to TOP2 poisons and/or a useful predictive biomarker for clinical response to these agents." (PMID 23505375, 2013).
tumor (continued). "Additionally, TDP2-high expression was associated with enriched signaling pathways involved in EMT, including COLLAGEN, GALECTIN, MIDKINE (MK), and ONCOSTATIN M (OSM), which promoted tumor cell migration, invasion, and immune evasion." (PMID 41481587, 2026). "The interaction between TDP2 high-expressing epithelial cells 2 and fibroblasts may further increase the synthesis and degradation of collagen, exacerbating the invasiveness of the tumor." (PMID 41481587, 2026). "We hypothesize that targeting TDP2 may have a role in reshaping the tumor immune microenvironment." (PMID 41481587, 2026). "For example, development of small molecule inhibitors for TDP2 may provide a way of sensitizing particular types of tumor to chemotherapy, though precaution is necessary to consider the possible consequences of TDP2 inhibition on normal cells and on the generation of secondary malignancies." (PMID 23505375, 2013). "TDP2 WT and TDP2 KD RM-1 cells were subcutaneously injected into immunocompetent C57BL/6J mice and immunodeficient nude mice, with tumor growth progress monitored regularly." (PMID 41481587, 2026). "CDCA7, CELSR3, PACS1, SNTB1, and TBC1D31 showed consistent upregulation in CRC tumor samples and pre-surgical cfRNA, while GFI1B, HPGD, SH3BGRL2, SIAE, PKHD1L1, and TDP2 showed downregulation in CRC tumor samples and pre-surgical cfRNA." (PMID 37091184, 2023). "Functionally, TDP2 overexpression suppresses M1 macrophage polarization, dendritic cell maturation, and CD8 + T cell activation, establishing an immunosuppressive milieu that favors tumor progression." (PMID 41481587, 2026). "Finally, our analysis revealed that TDP2 high-expressing epithelial cells utilize OSM signaling to enhance immune evasion, cell migration, and EMT, facilitating tumor metastasis." (PMID 41481587, 2026). "Additionally, TDP2 high expression also suppressed CD8 + T cell maturation, further enhancing the immune suppressive environment in the tumor microenvironment." (PMID 41481587, 2026). "We previously suggested that the inhibition of TDP2 combined with a TOP1 inhibitor and chain-terminating nucleoside analogs may be an effective strategy for tumor treatment." (PMID 40155951, 2025). "These inhibitors are not highly effective against purified Tdp1 and Tdp2 enzymes (ED50 for Tdp1/2 ranges from 1 to 40 μM) but suppress the growth of tumor cells in the nanomolar concentration range." (PMID 37895279, 2023). "In addition, we found that TDP2 high-expressing epithelial cells 2 may exert their effects through COLLAGEN, GALECTIN, MK, and OSM signaling pathways in tumor progression." (PMID 41481587, 2026). "We set out to validate the expression of the three cfRNA biomarkers – HPGD, PACS1, and TDP2 identified in our in-house cfRNA and CRC tissue samples using an independent cohort of pre- and post-surgical cfRNA samples (N=36) and published TCGA CRC tumor and tumor-adjacent samples (N=453)." (PMID 37091184, 2023).